SNORD14E (small nucleolar RNA, C/D box 14E)
Gene: Small nucleolar RNA gene on chromosome 11 (123,058,077 to 123,058,161, reverse strand). Ensembl gene ENSG00000200879.
Homologues: Orthologues: chimpanzee SNORD14 (95% identical), mouse Snord14e (82% identical), guinea pig SNORD14E (80% identical). Paralogues in human: SNORD14A (80% identical), SNORD14B (79% identical), SNORD14 (71% identical), SNORD14D (68% identical), SNORD14C (67% identical).
Diseases named in the same sentence as SNORD14E in open-access papers:
SNORD14E is named in the same sentence as 2 diseases in open-access papers, as found by Europe PMC text mining. Sharing a sentence is not in itself a finding about the gene and the disease. The quoted sentences say what the papers report.
Huntington disease (1 paper, 2016). Huntington disease (HD) is a rare neurodegenerative disorder of the central nervous system characterized by unwanted choreatic movements, behavioral and psychiatric disturbances and dementia. "Very recently, studies reported that heat-stress–related genes like SNORD14E is associated with the neurodegenerative disorders such as AD, Parkinson’s disease and Huntington disease." (PMID 27050411, 2016).
SNORD14E also shares sentences with these, for which no sentence is quoted: Parkinson disease (1 paper).